IDH1 (isocitrate dehydrogenase (NADP(+)) 1)
Diseases named in the same sentence as IDH1 in open-access papers (continued):
Sharing a sentence is not in itself a finding about the gene and the disease.
glioma (continued). "Subsequently it was found that IDH1 mutations are present in the large majority of low grade gliomas (LGG) and define secondary GBM more rigorously than before." (PMID 25849072, 2015). "As the most frequent mutation, IDH1(R132H) has been served as a predictive marker of glioma patients." (PMID 26485760, 2015). "The prognostic role of IDH1 in gliomas: IDH1 mutation demonstrated by many studies as associated with prolonged survival." (PMID 27275230, 2015). "A peptide containing mutant (R132H) IDH1 has been shown to be immunogenic suggesting the potential for a mutation-specific vaccine for IDH1-mutant gliomas." (PMID 25785247, 2015). "TCGA data shows that increase in mutation rate in high grade phenotype was observed in both 1p19q co-deleted and intact gliomas with IDH1 mutation." (PMID 26524630, 2015). "IDH1 mutations, which are commonly observed in gliomas and leukemias, were found in two cases of our cohort." (PMID 26315110, 2015). "Our current study combined IDH1/2 mutated tumors with either 1p/19q codeletion or TERTp mutation as IDHmut-OT gliomas since both of the markers were closely associated with oligodendroglial differentiation with the presence of IDH1/2 mutation." (PMID 26369702, 2015). "We investigated the correlation of Ki-67 expression with IDH1/2 mutation status and their impact on clinical outcome in 703 gliomas." (PMID 26338964, 2015). "IDH1/2 mutations in glioma are thought to be principal events in early-stage gliomagenesis, and their oncometabolite, 2-HG, is responsible for multiple activities involved in tumor development." (PMID 26008980, 2015). "In conclusion, both our data and those of Platten and coworkers converge in supporting a translational evolution of immunological targeting of the R132H mutation of IDH1 in glioma patients." (PMID 25849072, 2015). "The identification of isocitrate dehydrogenase 1 (IDH1) mutations in glioma is one of the major discoveries mediating metabolomics and oncogenesis." (PMID 26008980, 2015). "To further detail the glioma molecular classification, we designed a glioma classification model based on IDH1/2 mutation status and Ki-67 expression level." (PMID 26338964, 2015). "G-CIMP tumors, a subgroup of Proneural subtype, were more prevalent among lower-grade gliomas, displayed distinct copy-number alteration and were tightly associated with IDH1 somatic mutations." (PMID 26502731, 2015). "We therefore confirmed that the IDH1 mutation is a positive prognosis marker in low-grade glioma patients." (PMID 26485760, 2015). "In glioma, the presence of an IDH1 mutation is actually associated with better prognosis than that of wild‐type tumours." (PMID 25864878, 2015). "Olar and colleagues investigated a large cohort of lower-grade gliomas to determine the prognostic role of histological grade and mitotic index following stratification by IDH1/2 mutation." (PMID 26369702, 2015). "Sequencing data showed that 19 of the 62 glioma patients (30.65%) had a IDH1(R132H) mutation in our cohort, whereas the detection rates of ddPCR and qRT-PCR were 33.87% and 27.42%, respectively." (PMID 26485760, 2015). "Secondary or lower-grade gliomas are commonly associated with IDH1 mutations, and IDH1 mutations have been recently associated with TGF-β signaling." (PMID 25529192, 2015). "Mutations in the isocitrate dehydrogenase enzyme isoform 1 (IDH1) or 2 (IDH2) genes have been frequently identified in gliomas." (PMID 26158269, 2015). "In conclusion, we have discovered a relationship between enhanced 5-ALA fluorescence and IDH1 mutations in WHO grade III gliomas." (PMID 26008980, 2015). "Because IDH1 gene status is a powerful prognostic indicator for infiltrative gliomas, we also evaluated the relationship between its mutation status and CD151 expression in our patient cohort." (PMID 26377974, 2015). "Our study provided complementary results as to the prognostic role of IDH1 mutation relative to histological grade in lower-grade gliomas." (PMID 26369702, 2015).
glioma (continued). "In particular, mutation of IDH1 gene in gliomas has been shown to influence the methylation of a number of pro-malignant genes, and is strongly associated with CD151 expression in our patient cohort." (PMID 26377974, 2015). "Promoter mutation of telomerase reverse transcriptase (TERTp) is another emerging molecular marker which can stratify lower-grade gliomas and glioblastomas into prognostic subgroups, particularly in combination with IDH1 mutation." (PMID 26369702, 2015). "The R132H mutation of cytosolic isocitrate dehydrogenase (IDH1) is present in the majority of low grade gliomas." (PMID 25849072, 2015). "The IDH1 mutation is one of the most common and earliest genetic alterations in glioma and is an effective diagnostic and predictive marker in glioma patients." (PMID 26485760, 2015). "Mutations of the IDH1/2 genes represent significant driver mutations in gliomas and acute myeloid leukemia development, but are quite rare/almost undetectable in solid tumors." (PMID 26372729, 2015). "In a previous study, we investigated whole-chromosome copy number aberrations (CNAs) of gliomas and have described genetic subgrouping based on CNAs and IDH1 mutations." (PMID 26558387, 2015). "The data demonstrated that IDH1 mutant gliomas with −1p/19q and +7q CNAs are associated with a better prognosis than that associated with IDH1 wild-type gliomas." (PMID 26558387, 2015). "Examination of glioma samples from patients also showed that mutations in IDH1 were associated with increased histone methylation and decreased 5-hydroxymethylcytosine (5hmC) levels." (PMID 26231040, 2015). "To address this, we stably transfected a human glioma cell line, U251, with vectors encoding the wild-type or the mutant form of IDH1 (IDH1R132)." (PMID 25811801, 2015). "IDH1 mutations were found to be correlated with high frequency of CpG island methylation events in gliomas and subsequently shown to be a causative factor in this regard." (PMID 25468711, 2015). "Genetic subgrouping of gliomas has been emphasized recently, particularly after the finding of isocitrate dehydrogenase 1 (IDH1) mutations." (PMID 26558387, 2015). "While co-occurrence of 19q loss and IDH1 mutations has been found to diminish the survival advantage conferred by the IDH1 mutation in low-grade glioma, nothing has been reported so far about IDH1 and 11p15 loss co-occurrence." (PMID 25953855, 2015). "In the current study, we collected 62 glioma tissue samples (Grade II to IV) and detected IDH1 mutations by Sanger direct sequencing, ddPCR, and quantitative real-time PCR (qRT-PCR)." (PMID 26485760, 2015). "The c.395G > A (R132H) mutation in IDH1 was the most common one, present in 94 cases (94%); two gliomas harbored the IDH1 c.394C > T mutation (R132H)." (PMID 25797251, 2015). "Pubmed and EMBASE databases were searched for studies reporting IDH mutations (IHD1/2 and IDH1) and survival in gliomas." (PMID 26220714, 2015). "Parsons (2008) firstly proposed the presence of mutations in the active site of IDH1/2 in most low-grade gliomas and secondary high-grade gliomas." (PMID 26220714, 2015). "IDH1 mutation, somatic mutation in isocitrate dehydrogenase 1 gene, occurs at high frequency in gliomas and seems to be a prognostic factor in glioblastoma patients." (PMID 26502731, 2015). "IDH1 mutations in glioma cells diminish the canonical enzymatic activity of IDH1 while conferring a neomorphic enzymatic activity: the production of R-2-hydoxyglutarate (2-HG) via the consumption of NADPH." (PMID 26008980, 2015). "Despite the low score obtained using the class I MHC binding prediction we immunized immune competent IDH1 mutated glioma-bearing mice using four short peptides (two 9-mers and two 10-mers)." (PMID 25849072, 2015). "In a recent study, an immune response generated against unique epitopes expressed on IDH1 mutated gliomas was successful in a mouse model using a peptide-based vaccine." (PMID 26646075, 2015).
glioma (continued). "This is contributing to the development of leukemia, glioma and cholangiocarcinoma, respectively, all of which are described to have IDH1 or -2 mutations in a relatively high percentage of tumors." (PMID 26046462, 2015). "We have analyzed genomic data using next-generation sequencing technology for longitudinal samples from 3 patients with IDH1-mutated gliomas whose disease had progressed from a low grade to a high grade phenotype." (PMID 26524630, 2015). "We used two Kaplan-Meier survival analysis methods, the Log-rank and Breslow tests, to evaluate the role of the IDH1 mutation in the prognosis of glioma patients (Grade II and III)." (PMID 26485760, 2015). "We successfully applied ddPCR to detect the frequent mutation of IDH1 in glioma patient tissue samples in the current study." (PMID 26485760, 2015). "As previously identified, mutations in FUBP1 and IDH1 are closely associated with oligodendrogliomas, and are important prognostic and molecular markers for differentiating glioma phenotypes." (PMID 26246470, 2015). "We combined IDH1/2 mutation status with Ki-67 expression level to describe the biological properties and prognosis for each patient quickly and precisely in 703 gliomas." (PMID 26338964, 2015). "The causative factors implicated in the methylator phenotype are currently emerging with exciting advances taking place in gliomas following the identification of acquired mutations in the IDH1 gene." (PMID 25468711, 2015). "Within histologies, the only molecularly identical patients were the three patients with primary CNS glial tumors with solitary IDH1 R132H mutation." (PMID 26418953, 2015). "Recent investigations implicated IDH1/2 mutation in the classification of biologically distinct groups of gliomas, and indicated improved outcome." (PMID 26338964, 2015). "In conclusion, IDH1 mutation is commonly present in adult gliomas particularly low-grade gliomas, and secondary glioblastoma, with no sex predilection, but it has no role in pediatric gliomas." (PMID 27275230, 2015). "Recently, it was demonstrated that HIF-1α-responsive genes essential for cell growth, including LOX, were underexpressed in gliomas with IDH1 mutation." (PMID 25790191, 2015). "Taken together, both IDH1/2 mutation and Ki-67 expression level are reliable prognostic markers of gliomas." (PMID 26338964, 2015). "On the other end, IDH1/2 wild-type tumors with either TERTp mutation or EGFR amplification were defined as IDHwt-ET gliomas." (PMID 26369702, 2015). "Recently, isocitrate dehydrogenase 1/2 (IDH1/2) was shown to be mutated in up to 70%–80% of low-grade gliomas (grades II and III)." (PMID 26468983, 2015). "Somatic mutations in isocitrate dehydrogenase (IDH)-1 and -2 have recently been described in glioma." (PMID 25811801, 2015). "Several previous studies have demonstrated the important prognostic role of IDH1 mutations in patients with high-grade gliomas." (PMID 26115094, 2015). "Mutations in isocitrate dehydrogenase 1 and -2 (IDH1 and -2) genes are found in acute myeloid leukemia (~20%), gliomas (60-80%), cholangiocarcinomas (7-28%) and in benign and malignant cartilage tumors." (PMID 25895133, 2015). "It has also been suggested that the distant appearance of recurrent gliomas are associated with IDH1 mutation and TMZ-induced mutagenesis." (PMID 26466313, 2015). "Somatic heterozygous IDH1 or IDH2 mutations have frequently been detected in glioma/glioblastomas by genome wide mutation searches." (PMID 26161668, 2015). "Since the OncoPanel sequencing platform includes IDH1 and IDH2, we sought to characterize the spectrum of IDH1/2 mutations given the important clinical and prognostic implications of IDH1/2 mutations in gliomas." (PMID 25257301, 2014). "The mechanisms underlying the effect of IDH1 mutation on the enhanced prognosis of glioma patients was also investigated, in the hope of providing clues to improve glioma therapy." (PMID 24520288, 2014).
glioma (continued). "The discovery of TERT promoter mutations in these subsets of gliomas creates an opportunity for genomics to supplement histopathological analysis, especially when combined with IDH1/2 mutation status." (PMID 24722048, 2014). "IDH1/2 mutations are the most frequent mutations detected in lower grade gliomas and those tumors associated with IDH1/2 mutation are reported to have better outcomes compared to wild type tumors." (PMID 25257301, 2014). "Testing for the presence of an IDH1/2 mutation is now considered by international guidelines for glioma management." (PMID 24889502, 2014). "Complete 1p19q codeletion was found in 150 gliomas: the IDH1 gene was mutated in 137 cases (91.3%) and the IDH2 gene was mutated in 12 of the 13 remaining tumors." (PMID 24877111, 2014). "In this large series, we investigated the place of IDH1/IDH2 mutation in gliomas, in particular in different genotypes and phenotypes." (PMID 24877111, 2014). "Due to IDH1 mutation, glioma is associated with two subtypes which bring about distinctly different prognoses." (PMID 24520288, 2014). "Numerous studies have identified IDH1/2 mutations as a more powerful prognostic marker in glioma patients, and found that IDH mutational status delineates molecularly and clinically distinct subclasses of gliomas." (PMID 24810474, 2014). "In summary, we have developed a new PCR-based assay which enables rapid and simple detection of the major IDH1 R132H mutation and of 11 rarer IDH1/2 ones in FFPE glioma samples." (PMID 24889502, 2014). "Isocitrate dehydrogenase 1 (IDH1) mutation has been reported to be associated with an increased overall survival in patients with glioma in a number of studies." (PMID 24520288, 2014). "Analysis of the effect of heterozygous IDH1 mutations on glioma cells has shown that mutant IDH1 affects the ability of the enzyme to reduce α-ketoglutarate to 2-hydroxyglutarate (2HG)." (PMID 24868540, 2014). "Since then, the IDH1 mutation has been recognized as the most frequent alterations in gliomas, occurring in 40% of glial tumors and is the most powerful prognostic factor ever described in gliomas." (PMID 24877111, 2014). "The accumulation of 2-hydroxyglutarate (2HG) is noted in the cytoplasm of glioma cells with IDH1 mutation and in the mitochondria of cells with IDH2 mutation." (PMID 25376594, 2014). "The distinctive mutation IDH1 R132H was uncovered to be a strong prognostic biomarker for glioma patients." (PMID 24511544, 2014). "It has also been shown that the IDH-1 mutation is likely to occur during the earlier stages of glioma tumorigenesis; therefore, a large proportion of low-grade gliomas possess the IDH-1 mutation." (PMID 24765187, 2014). "In this study, we validated the performance of this new IDH1/2 PCR assay on a large cohort of FFPE glioma samples collected less than 10 years ago and on synthetic samples mimicking all 11 rare IDH1/2 mutations." (PMID 24889502, 2014). "This assay was further validated on a large series of FFPE glioma samples to determine the reliability of the method in a routine clinical setting, by comparing IDH1/2 mutation analysis with IHC and Sanger sequencing." (PMID 24889502, 2014). "Of these, perhaps one of the most notable has been the identification of mutations in the metabolic enzyme IDH1 in low-grade glioma and secondary glioblastoma." (PMID 24351290, 2014). "In this study, we characterized the impact of IDH1 mutation on U87 glioma cell growth and radiosensitivity." (PMID 24895549, 2014). "Mutations in isocitrate dehydrogenase 1 and 2 genes (IDH1/2) have been identified in >80% of ALGGs as well as a subset of GBMs that progressed from lower grade gliomas." (PMID 25257301, 2014). "New evidence suggests that IDH1 mutation inhibits the growth of glioma cells via GSH inhibition and generation of reactive oxygen species (ROS)." (PMID 25376594, 2014).
glioma (continued). "Specifically, 60–90% of low-grade gliomas and secondary glioblastomas harbor a heterozygous R132H mutation in the gene coding for the cytosolic isoform of isocitrate dehydrogenase (IDH1)." (PMID 25243911, 2014). "Glioma development is frequently associated with mutations of the isocitrate dehydrogenase IDH1 and IDH2 genes, whereas mutations of IDH3 have never been observed in GBM." (PMID 25050814, 2014). "This study demonstrated that, in this model, targeting mutant IDH1 can impair glioma growth in vivo and this growth inhibition is linked to changes in differentiation." (PMID 25147764, 2014). "The IDH1 mutation in low-grade gliomas is likely an early event in tumorigenesis and subsequent mutations follow, creating the characteristic cellular phenotype and natural history of disease in patients." (PMID 25243911, 2014). "The limiting step of our analyses was the low incidence of IDH1 mutations other than R132H in gliomas." (PMID 24529257, 2014). "The limiting step of our analyses was the low incidence of IDH1 mutations in gliomas other than R132H." (PMID 24529257, 2014). "In gliomas, the frequency of IDH1 mutations in codon 132 increases in the order R132L-R132S-R132G-R132C-R132H with R132H constituting more than 90% of all IDH1 mutations." (PMID 24529257, 2014). "IDH1 mutation downregulated glioma cell proliferation by blocking the cell cycle, reduced the cell invasion ability via MMP-2 and MMP-9 downregulation and promoted the cell migration ability." (PMID 24520288, 2014). "With open clinical trials for IDH1 mutant glioma patients, determining IDH1 mutational status for ALGG patients is critical for satisfying trial entry criteria." (PMID 25257301, 2014). "Our analysis of this tumor cohort expands upon previous reports identifying frequent TERT promoter mutations in gliomas, examines the association between TERT promoter and IDH1/2 mutations in glioma, and assesses their joint influence on OS." (PMID 24722048, 2014). "Tumors with mutated IDH1 and corresponding epigenetic changes demonstrated better prognosis than gliomas with wild-type IDH1." (PMID 24511544, 2014). "Confirming previous data obtained on smaller cohorts, our findings showed that gliomas patients harboring an IDH1 mutated tumor present an improved outcome, compared to patients with an IDH1 normal tumor." (PMID 24877111, 2014). "The presence of IDH1/2 mutations in both astrocytomas and oligodendrogliomas suggests that this mutation occurs early in glioma development, most likely in a stem/progenitor cell that can give rise to both cell types." (PMID 25257301, 2014). "IDH1/2 mutations typically occur in low-grade gliomas and anaplastic astrocytic, oligodendroglial and mixed oligoastroglial tumors and in secondary GBMs, but rarely in primary GBMs." (PMID 24810474, 2014). "We have screened for the presence of codon-132 mutations in the IDH1 gene in a large cohort of 1305 gliomas, including 436 WHO grade II, 394 WHO grade III, and 475 WHO grade IV gliomas." (PMID 24877111, 2014). "Mutations in IDH1/2 or TET have resulted in epigenetic alterations including a hypermethylated phenotype in gliomas and AML, respectively." (PMID 24140581, 2014). "Subsequent studies have shown that IDH2 mutations are also enriched in WHO grade II/III gliomas, albeit less frequently, and that IDH1/2 mutations occur in a mutually exclusive manner." (PMID 24622842, 2014). "Through analyzing, the percentage of IDH1 mutation is 73.9%, 43.1%, 22.0% and 22.6% for Proneural, Neural, Classical and Mesenchymal samples of all histological gliomas, respectively." (PMID 24755548, 2014). "Over 70% of low-grade gliomas carry a heterozygous R132H mutation in the gene coding for isocitrate dehydrogenase 1 (IDH1)." (PMID 25243911, 2014).